LOX (lysyl oxidase)
Diseases named in the same sentence as LOX in open-access papers (continued):
Sharing a sentence is not in itself a finding about the gene and the disease.
cancer (continued). "Some studies suggest that LOX is essentially involved in cancer cell invasion and progression through ECM remodeling." (PMID 32645959, 2020). "LOX expression was significantly higher in epithelial cells of colon mucosa 10 cm and 20 cm away from the cancer, compared with healthy mucosa (p < 0.0001)." (PMID 32286443, 2020). "Several types of cancer cells exhibit altered LOX expression or activity, and this is highly differentiated according to the involved LOX isoform, cancer cell type and the context." (PMID 32184727, 2020). "In human cells, Atox1 was found to mediate cancer cell migration by (via Cu transport) promoting extracellular, Cu-dependent, collagen-remodeling lysyl oxidase (LOX) activity." (PMID 32506305, 2020). "LOX is also being studied as a target for cancer metastasis owing to its incidence in various cancers." (PMID 32542505, 2020). "Under hypoxic conditions, LOX is secreted to mediate premetastatic niche formation and promote cancer metastasis." (PMID 33126606, 2020). "Despite this anti-tumor role documented for LOX-PP, and the reduced levels of some LOXs in a minority of cancers, the mature LOX, as well as other LOX family members, has a predominant pro-neoplastic activity." (PMID 31650200, 2020). "LOX, LOXL1, and LOXL2 were upregulated in certain kinds of cancers, and only LOX and LOXL2 were significantly elevated in RCC." (PMID 32970930, 2020). "LOX expression was significantly higher in lamina propria of colon mucosa 10 cm and 20 cm away from the cancer, compared with healthy controls (p < 0.0001 and p = 0.013)." (PMID 32286443, 2020). "One such mechanism involves upregulation within cancer cells of lysyl oxidase (LOX), an enzyme that catalyzes cross-linking of collagen with elastin fibers." (PMID 31574977, 2019). "The secretion of the enzyme lysyl oxidase (LOX) is upregulated in BM cancer cells, resulting in collagen hydroxilation grade changes that in turn alter tissue stiffness, a key factor in cancer growth." (PMID 31591367, 2019). "Cancer cells that were devoid of LOX that were injected into mice showed decreased osteolytic lesion formation." (PMID 31330786, 2019). "By crosslinking collagens and elastin in the ECM, LOX enzymes contribute to generating a stiff microenvironment that sustains cancer progression." (PMID 31130685, 2019). "The application of HIF as well as LOX-targeting drugs or antibodies inhibited metastasis in cancer cells." (PMID 31810265, 2019). "Amongst others, a functional role of LOX proteins has been described in breast, colorectal, pancreatic, prostate and ovarian cancers, in head and neck squamous cell carcinoma, renal cells carcinoma, uveal melanoma, and squamous cell skin carcinoma." (PMID 31130685, 2019). "Stromal fibroblasts contribute strongly to the elevated lysyl oxidase levels observed in many cancers." (PMID 32118030, 2019). "Although function is still not fully understood, it is thought that the lysyl oxidase (LOX) family of proteins is responsible for ECM remodeling in conjunction with matrix metalloproteases (MMP) in a way that promotes cancer metastasis." (PMID 30901831, 2019). "LOX plays an essential role in forming a pre-metastatic niche, creating a more favorable environment for the colonization of cancer cells at distant sites." (PMID 31121900, 2019). "For example, lysyl oxidase (LOX) secretion by cancer cells is upregulated at metastatic sites and contributes to tissue stiffness." (PMID 31330786, 2019). "The LOX family has been known to promote fibrosis and tumorigenesis, and accumulated evidence supports the use of β‐aminopropionitrile (βAPN) and simtuzumab to inhibit LOX and LOX‐L2 activities in fibrosis and cancer." (PMID 30538116, 2019). "For example, Lysyl Oxidase (LOX) is an ECM crosslinking enzyme that promotes stiffer ECM to drive cancer progression and metastasis, and targeting this protein has been shown to inhibit cancer progression and metastasis." (PMID 29642615, 2018).
cancer (continued). "Manipulation of LOX activity in vivo and ex vivo has been used to probe the role of tissue mechanics in the progression of cancer." (PMID 31069295, 2018). "BAPN, as a typical drug to inhibitor LOX, has shown promising anti-cancer effects in preclinical trial." (PMID 29458390, 2018). "The involvement of the LOX is accepted as a potential poor prognostic factor for patients with cancer." (PMID 29472856, 2018). "Since their extracellular presence is not unusual it remains interesting that cancer cells of solid tumors also revealed expression of those proteins, and an even stronger signal was observed for LOX in cancer cells than in extracellular matrix." (PMID 30583585, 2018). "Under these conditions, we observed LOX inhibitors decreased cancer cell viability, migration and EMT behavior." (PMID 30181809, 2018). "Our study emphasises the need to further dissect the functions of LOX family members in order to develop successful LOX targeted treatment strategies for fibrosis and cancer." (PMID 29953488, 2018). "In all instances elevated levels of LOX led to increased proliferation, migration, and invasion of cancer cells." (PMID 30583585, 2018). "Although tumor suppressive characteristics of LOX is still to be explored for better understanding, its contribution in promoting cancer is much more pronounced." (PMID 30128085, 2018). "LOX inhibition probably affects both normal cells and cancer cells by decreasing ECM deposition and maturation." (PMID 30181809, 2018). "It was also revealed that LOX secreted by hypoxic cancer cells acts to form a pre-metastatic niche by recruiting CD11b+ myeloid cells." (PMID 30423905, 2018). "The results obtained for LOX immunohistochemistry indicated the stronger expression of the protein in cancer cells than in extracellular matrix." (PMID 30583585, 2018). "COX-2 and LOX enzymatic activity and their byproduct have proved to be essential for cancer development of numerous cancers." (PMID 30245627, 2018). "have shown that metastasis of cancer cells can be promoted by the secretion of enzymatically active LOX by neighboring fibroblast cells." (PMID 28110559, 2017). "LOX expression was detected both in the cytoplasm and in the nucleus of normal epithelial cells and cancer cells." (PMID 28947950, 2017). "In survival analysis, high nuclear LOX expression in stage I to III cancers was correlated to poor overall cancer-specific survival (OS) (P = 0.017) and disease free survival (DFS) (P = 0.049)." (PMID 28947950, 2017). "Advanced cancer cells such as CL1-5 cells can secrete lysyl oxidase (LOX), an extracellular copper enzyme that oxidizes lysine residues in elastin and collagen to form covalent cross-linking between these fibrous proteins that can stiffen the matrix." (PMID 27505887, 2017). "LOX is secreted by cancer cells to create pre-metastatic niches by stimulating collagen cross-linking and fibronectin synthesis." (PMID 28425924, 2017). "Ectopic LOX expression was found to inhibit Ras-mediated transformation, and decreased LOX expression has been reported in several types of cancers." (PMID 28947950, 2017). "Some amine oxidases have been reported to be involved in regulating cancers; LOX has played an important role in colorectal cancer cell dissemination in the bone marrow, and expression of AOC3 is associated with cancer prognosis in various tumors." (PMID 29261141, 2017). "Taken all of these results together, it has been highly implied that nuclear localisation of LOX plays an important role in the process of cancer metastasis." (PMID 28947950, 2017). "Hypoxia-driven cancer cell invasion is severely impaired when LOX expression or oxidase activity were inhibited." (PMID 28143503, 2017). "Here, we found that A2M* treatment of A549, HT29, LOX and MDA-MB231 cancer cells caused up-regulation of the PTEN protein." (PMID 29281661, 2017).
cancer (continued). "Mechanistic information for how some copper-binding proteins, such as extracellular lysyl oxidase (LOX), play roles in cancer have been elucidated but there is still much to learn from a biophysical molecular viewpoint." (PMID 28425924, 2017). "Several studies have investigated the mechanistic role of extracellular LOX in cancer cell invasion and metastasis." (PMID 28425924, 2017). "Such inhibitors would be important not only as potential drug candidates, but also as chemical tools to study LOX-related biological mechanisms that are involved in cancer metathesis and other diseases." (PMID 28110559, 2017). "Altogether, our results show that enhanced STAT3 activity achieved upon RIP4 down-regulation promotes the expression of ECM remodeling genes such as LOX, which contributes to cancer cell de-differentiation and metastasis." (PMID 28574510, 2017). "Altered LOX localisation was further confirmed by confocal microscopy and Western blot in cancer cell lines." (PMID 28947950, 2017). "It sheds a new light on better understanding the complex and crucial role of LOX in cancer beyond its well-known extracellular matrix-modifying function." (PMID 28947950, 2017). "One explanation for the seemingly paradoxical role of LOX in cancer is likely the existence of multiple forms and differential localisation of LOX." (PMID 28947950, 2017). "We have provided the mutations of the two cell lines in question (LOX-IMVI and A375) in a table that can be imported, downloaded from the Cancer Cell Line Encyclopedia." (PMID 29023449, 2017). "Here we have identified an unexpected role of LOX (a) in cell cycle regulation and (b) in cancer cell mitosis by directly interacting with microtubules." (PMID 27296552, 2016). "Infact, over expression of COX and LOX in progression and neo-angiogenesis of human cancer has been supported by large body of scientific literature." (PMID 27473871, 2016). "LOX can be a molecular target for anti-cancer treatment, as it has been reported to increase migration, invasion, and metastasis dissemination through its capacity to regulate collagen cross-linking and ECM stiffening in different kinds of cancer." (PMID 28036074, 2016). "On other hand, it is confirmed that LOX pathway receptor expression was found in the majority of cancers evaluated specifically in ovarian cancer." (PMID 27231478, 2016). "Knockdown of LOX in cancer cells resulted in a progression through S phase with normal kinetics, followed by a significant increase of 4N cells." (PMID 27296552, 2016). "Several studies have shown that LOX transcription is increased in tumors of the breast, central nervous system, and head and neck, among others, as well as in various cancer cell lines." (PMID 26882568, 2016). "LOX overexpression was also associated with EMT and stemness of cancer cells, which leads to chemotherapeutic resistance and poor outcome in ER– patients." (PMID 27147578, 2016). "Aberrant expression or activation of LOX often leads to many diseases including tissue fibrosis and cancer." (PMID 28036074, 2016). "LOX knockdown leads to G2/M phase arrest; reduced p-H3(Ser10), cyclin B1, CDK1, and Aurora B. Moreover, LOX knockdown significantly increased sensitivity of cancer cells to chemotherapeutic agents that target microtubules." (PMID 27296552, 2016). "Knockdown of LOX increased the anti-proliferative effect of docetaxel in the 3 cancer cells, and increased the antiproliferative effect of vincristine in THJ-16T and HeLa cells." (PMID 27296552, 2016). "The reasons for the contradictory results obtained for LOX in various cancers is likely multifactorial." (PMID 26882568, 2016). "LOX also plays a role in cancer by enhancing cancer cell proliferation, invasion, metastasis, and angiogenesis." (PMID 28036074, 2016). "For example, increased LOX expression levels have been found in a wide range of cancers, including pancreatic, bladder, and breast cancer." (PMID 27047380, 2016).
cancer (continued). "Consistent with LOX playing an important role is the finding that its expression is increased in several types of malignant tumors as well as various cancer cell lines." (PMID 26882568, 2016). "Recently, it has become evident that LOX is involved in increased malignancy and invasiveness in a variety of human cancers." (PMID 26908052, 2016). "While some investigators have used this agent as a target of the LOX pathway in cancer, more recent studies have focused on the anti-cancer effects of this compound and elucidating the mechanisms underlying these effects." (PMID 27586635, 2016). "LOX and LOX family members are frequently overexpressed in cancers, and their collagen cross-linking activity has been proven to promote tumor progression through increased integrin signaling." (PMID 26539408, 2015). "Together with the critical role that LOX plays in maintaining the properties of the connective tissues, it has been also shown to play important roles in cancer." (PMID 26258070, 2015). "HMGA2 plays important roles in promoting cancer metastasis by downregulating miR-200b expression and increasing the level of lysyl oxidase (LOX)." (PMID 25868853, 2015). "Functional molecular imaging of LOX enzyme expression in vivo would open novel opportunities for non-invasive detection, staging and monitoring therapy of cancer." (PMID 26265048, 2015). "The LOX active site small-molecule antagonist BAPN has been investigated for a long time as a potential drug for cancer therapy." (PMID 26265048, 2015). "The first evidence of a relationship between LOX and cancer comes from experiments designed to identify genes involved in Ras-mediated transformation of NIH-3T3 mouse fibroblasts." (PMID 26258070, 2015). "Administering cancer cell-conditioned media was sufficient for the induction of osteolysis, and this enhanced bone colonization in a LOX-dependent manner." (PMID 26337273, 2015). "The present data support further investigation into the development of LOX-binding radiolabeled peptides as molecular probes for molecular imaging of LOX expression in cancer." (PMID 26265048, 2015). "LOX expression correlates with poor survival and is a therapeutic target for patients with certain cancers, while LOXL2 is a focus in the monitoring and treatment of fibrotic lung disease." (PMID 30155003, 2015). "Lysyl oxidase is known to play an important role in hypoxia-dependent cancer cell dissemination and metastasis." (PMID 25052686, 2014). "LOX is regulated by hypoxia-inducible factors (HIFs) and has been reported to be upregulated in a number of cancers." (PMID 24950699, 2014). "Accordingly, it is important to characterize metastasis promoters such as LOX in the context of survival and established clinical and histopathological characteristics of human cancer." (PMID 25141126, 2014). "Both up- and downregulation of LOX have been observed in different cancer cell lines and primary tumors." (PMID 23545606, 2013). "The primary molecular abnormality in EBV associated LLC of the stomach is global and non-random CpG island methylation in the promoter region of many cancer-related genes (such as LOX, HRASLS, FLNC, HAND1, and THBD)." (PMID 24188515, 2013). "The identification of hypoxia-HIF-1α-LOX pathway provides novel insights into the mechanisms that control cancer cell migration in hypoxia and reoxygenation regions." (PMID 23545606, 2013). "It is in this function where LOX is enhanced in hypoxic tumors, promoting signaling through focal adhesion kinase, and thus contributing to the invasive properties of hypoxic cancer cells." (PMID 22275804, 2012). "CHL1 behavior in cancer is thus strikingly similar to L1 and LOX which both work through the actin network." (PMID 21408220, 2011). "Several genes that encode these proteins were upregulated in the CD26+ cancer cells: AGR2, BCMP11, CEACAM5/CD66e, CRISP3, KCNG3, KCNH8, LOX and NEO1." (PMID 20021671, 2009).
cancer (continued). "Therapeutically, LOX inhibition could concurrently benefit fibrosis and cancer treatment, such as LOXL2 inhibitors reducing ECM stiffness in fibrotic tumors to improve drug efficacy." (PMID 40661776, 2025). "In the past 30 years, 2490 LOX - related publications in the cancer domain were unearthed." (PMID 40661776, 2025). "LOX, an extracellular matrix regulator, plays a pivotal role in cancer metastasis." (PMID 39857068, 2025). "This implies that treatments targeting LOX should be selective, targeting only those cancers where LOX promotes progression, potentially necessitating molecular diagnostic tools, and that LOX or its by-products could potentially serve as anticancer agents." (PMID 40661776, 2025). "LOX’s diverse functions and its links to cancer and fibrosis." (PMID 40661776, 2025). "In the cancer - related LOX study, 137 authors were involved." (PMID 40661776, 2025). "Cancer-associated fibroblasts (CAFs) secrete collagen and fibronectin under SASP influence, while lysyl oxidase (LOX)-mediated ECM crosslinking increases tissue stiffness, activating integrin-FAK signaling to accelerate metastasis and confer therapy resistance." (PMID 40510156, 2025). "This work highlights the importance of LOX in facilitating cancer cell migration and metastasis, with implications for the developments of novel therapeutics combating the progression of cancer." (PMID 38495620, 2024). "Furthermore, silencing VDAC1 in cancer cells impacted the expression of structural proteins, matrix metalloproteinases, and lysyl oxidase (Lox), triggering a stromal response similar to that observed during wound healing." (PMID 39456237, 2024). "The aberrant expression and accumulation of LOX is common for various types of cancer." (PMID 39329988, 2024). "Importantly, our single-cell sequencing data included both normal and cancer tissues, allowing us to investigate how LOX+ Fibroblasts change during TME formation." (PMID 39251966, 2024). "However, CA9 was dominating in the cancer cell lines, whereas LOX and LOXL2 were dominating in the fibroblasts." (PMID 39011470, 2024). "Our work suggests that targeting LOX could serve as a promising anti-cancer treatment in obese patients." (PMID 38468823, 2024). "Besides of LOX and LOXLs, WISPs can also mediate collagen I linearization to control cancer metastasis." (PMID 36906534, 2023). "Fisher’s exact test (2X2 analysis) between knockin mice treated with 4 NQO vs. wildtype (Arg LOX-PP) treated with 4 NQO indicated that the incidence of cancer in the Gln LOX-PP knockin mice treated with 4 NQO is more significant compared to the mice treated with 4 NQO (p < 0.05)." (PMID 37298359, 2023). "Furthermore, the clinical diagnosis of cancer and fibrotic diseases will be improved by allysine-reactive probes and lysyl oxidase-directed tracers." (PMID 37565736, 2023). "Among these strategies, targeting lysyl oxidase (LOX) activity that is frequently upregulated in diverse cancer types and responsible for catalyzing collagen crosslinking is emerging as a optimal one, which can reduce the stroma density and consequently enhance the outcome of anticancer treatment." (PMID 36324128, 2022). "Besides the specific role of each LOX member plays in cancer, the involvement of several members of LOXs has also been illustrated." (PMID 35433829, 2022). "In addition, Lysyl oxidase (LOX) and its family members LOXL1-4, the copper-dependent amine oxidases playing critical roles in ECM crosslinking and remodeling, are implicated in cancer progression and metastasis." (PMID 36003792, 2022). "Studies have shown that LOX leading to cancer niches where tumors can develop and metastasize." (PMID 35189882, 2022). "Cancer cell-secreted LOX increases matrix stiffness and volume." (PMID 36114508, 2022). "have reported the relationship between LOX expression and pan-cancers using meta-analysis." (PMID 36202905, 2022).